TOB1 (transducer of ERBB2, 1)
Diseases named in the same sentence as TOB1 in open-access papers (continued):
Sharing a sentence is not in itself a finding about the gene and the disease.
pancreatic cancer (2 papers, 2020 to 2023). "We next analyzed the association between TOB1 protein expression levels and survival time in 97 pancreatic cancer patients." (PMID 31891232, 2020). "TOB1 overexpression prevented the cell transition from G1 phase to S phase, and caused the proliferation of K‐Ras wild‐type pancreatic cancer cells was inhibited, at least in part through the calcium pathway." (PMID 31891232, 2020). "After observation of the reversal of the malignant phenotype of pancreatic cancer cells by overexpressing TOB1, we explored the underlying molecular mechanisms." (PMID 31891232, 2020). "To evaluate the clinical significance of TOB1 in pancreatic cancer, we analyzed the association between TOB1 expression and patients' clinicopathological characteristics." (PMID 31891232, 2020). "Among them, CASP4, TOB1, and CLEC2B were associated with poorer prognosis in pancreatic cancer patients, while FYN showed a correlation with better prognosis." (PMID 37753069, 2023). "CASP4, FYN, TOB1, and CLEC2B exhibited close associations with infiltrating Treg cells in pancreatic cancer, suggesting their involvement in Treg cell functions." (PMID 37753069, 2023). "TOB1 overexpression decreased expression of Cyclin D1, CDK2 and CDK4, and caused proliferation inhibition of K-Ras wild‐type pancreatic cancer cells, at least in part through the calcium pathway." (PMID 31891232, 2020). "To identify related genes that are regulated by TOB1 in pancreatic cancer, we performed RNA‐Seq analyses of controls or transfectants." (PMID 31891232, 2020). "In this study, we explored the expression and mechanisms of TOB1 in regulating the malignant phenotype of pancreatic cancer cells." (PMID 31891232, 2020). "In summary, Foxa2, as a transcription factor of TOB1, regulates its mRNA expression, while TOB1 participates in the anti‐pancreatic cancer process by regulating the expression of calcium pathway genes." (PMID 31891232, 2020). "Compared with normal pancreatic tissues, pancreatic cancer tissues showed substantially decreased TOB1 mRNA and protein levels." (PMID 31891232, 2020). "We found TOB1 was downregulated in pancreatic cancer tissues and was mainly located in the cytoplasm." (PMID 31891232, 2020). "Overexpression of TOB1 can partially reverse the malignant phenotype of K‐Ras wild‐type pancreatic cancer cells by regulating calcium pathway genes." (PMID 31891232, 2020). "Low expression of TOB1 was detected in pancreatic cancer tissues and inversely correlated with tumor size." (PMID 31891232, 2020). "To clarify the expression of TOB1 in pancreatic cancer, we explored the mRNA and protein expression of TOB1 in pancreatic samples via the Oncomine database and immunohistochemistry (IHC)." (PMID 31891232, 2020). "In summary, our study demonstrates that TOB1 expression is downregulated in human pancreatic cancer." (PMID 31891232, 2020). "We discussed TOB1 expression and its clinical significance in pancreatic cancer tissues." (PMID 31891232, 2020). "However, few research have examined the expression and biological role of TOB1 in pancreatic cancer." (PMID 31891232, 2020). "In addition, by analyzing the correlation between TOB1 protein and the clinicopathological features of pancreatic cancer patients, we found that larger cancer tissues had a lower TOB1 protein level." (PMID 31891232, 2020). "In conclusion, TOB1 may suppress the proliferation of K‐Ras wild‐type pancreatic cancer cells by regulating calcium pathway genes." (PMID 31891232, 2020). "To sum up, we concluded that TOB1 expression is downregulated in pancreatic cancer and may act as a tumor suppressor." (PMID 31891232, 2020). "Moreover, overexpressing TOB1 substantially enriched the calcium pathway in K‐Ras wild‐type pancreatic cancer cells." (PMID 31891232, 2020).
pancreatic cancer (continued). "Given that TOB1 is involved in regulating the biological behaviors of various tumors, we examined whether TOB1 acts as a tumor suppressor in pancreatic cancer cells by utilizing a gain‐of‐function approach." (PMID 31891232, 2020). "Notably, TOB1 protein expression was significantly correlated with tumor size, suggesting that TOB1 may play a role in negatively regulating the growth or proliferation of pancreatic cancer cells." (PMID 31891232, 2020). "Therefore, we tried to explore whether altering TOB1 expression could affect the development of pancreatic cancer and elucidate its potential mechanism." (PMID 31891232, 2020). "During previous decades, growing evidence has emphasized the rising importance of TOB1 in diversified human cancers, but how TOB1 works in pancreatic cancer has not been fully expounded." (PMID 31891232, 2020). "Taken together, these results indicate that the mechanism of TOB1 against pancreatic cancer might be an antiproliferative effect rather than inhibition of invasion or metastasis in BxPC‐3 cells in vitro." (PMID 31891232, 2020).
Alzheimer disease (1 paper, 2023). A progressive, neurodegenerative disease characterized by loss of function and death of nerve cells in several areas of the brain leading to loss of cognitive function such as memory and language. "Among the top hub genes associated with the common factor, TOB1, RANBP9, HSPB3, and SRSF3 were also linked to neurodegenerative disorders, such as Alzheimer’s disease, Parkinson’s, and amyotrophic lateral sclerosis, through various pathways." (PMID 36959830, 2023).
asthma (1 paper, 2025). "Previous RNA-seq data showed that inflammation and extracellular matrix remodeling pathways were affected by Tob1 and Mub2 expression in several diseases, including asthma." (PMID 40313552, 2025). "Additionally, subjects with severe asthma were more sensitive to low, high temperature and temperature fluctuation conditions, with increased of Tob1, Mub2, Sic34a2, Sftpc, Nxnl, Luc71, Lamp3, Gpr171, Cox14, and Cd3e expression." (PMID 40313552, 2025). "We observed that the mild, moderate, and severe asthma subject in the extreme low temperature group showed increased Tob1, Mub2, Sic34a2, Sftpc, Nxnl, Luc71, Lamp3, Gpr171, Cox14, and Cd3e expression, while in the severe asthma subjects showed increased expression in all temperature exposure group." (PMID 40313552, 2025).
Autoimmunity (1 paper, 2016). The occurrence of an immune reaction against the organism's own cells or tissues. "Since TOB1 regulates the threshold of activation of naive T cells; acting like a brake to ensure cells do not become activated in response to inappropriate stimulation, reduced TOB1 expression in T cells is implicated in the development and progression of autoimmunity." (PMID 27386265, 2016).
bipolar disorder (1 paper, 2012). A disorder of the brain that causes unusual shifts in mood, energy, activity levels and the ability to carry out day-to-day tasks. "For example, TOB1 expression is altered in the frontal cortex of patients with bipolar disorder, while molecular interference with the TOB1 protein suppresses long-term potentiation and impairs spatial learning and memory in rats." (PMID 23087602, 2012).
brain cancer (1 paper, 2017). A primary or metastatic malignant neoplasm affecting the brain. "With respect to brain cancer, increased TOB1-2 and BTG3 revealed poor prognosis, while higher BTG2 was related to better prognosis." (PMID 28922388, 2017). "Moreover, we had some other new discoveries that downregulated TOB1 mRNA expression implied better overall survival (OS) in brain cancer patients." (PMID 28922388, 2017).
chondrosarcoma (1 paper, 2005). A malignant cartilaginous matrix-producing mesenchymal neoplasm arising from the bone and soft tissue. "Tob1 expression was also detected at a decreased level in isolated chondrocytes and in the chondrosarcoma cell line HCS-2/8." (PMID 15743474, 2005).
demyelination (1 paper, 2016). "Given the physiological role of Tob1 in modulating gene expression at multiple levels, here we further dissect its contribution to autoimmune demyelination by analyzing the molecular pathways controlled by Tob1 in the immune system upon EAE induction." (PMID 27546286, 2016).
ductal breast carcinoma in situ (1 paper, 2017). A carcinoma entirely confined to the mammary ducts. "In Ma’s dataset, we found that TOB1 was more highly expressed in both ductal breast carcinoma in situ and invasive ductal breast carcinoma, while we obtained an opposite conclusion from Finak’s dataset." (PMID 28922388, 2017).
embryonic cancer (1 paper, 2015). "A recent study indicated that TOB1 may be involved in the inhibition of human embryonic cancer stem cell proliferation as the depletion of Nanog, a key transcription factor that maintains pluripotency, increased TOB1 expression and down-regulated the expression of cyclins, CDK1 and CDK6." (PMID 26694352, 2015).
endometriosis (1 paper, 2014). The growth of functional endometrial tissue in anatomic sites outside the uterine body. "Furthermore, expression of negative regulators of EGFR signaling, TOB1 and MIG6, has been found to be reduced in women with endometriosis." (PMID 24945252, 2014).
esophageal squamous cell carcinoma (1 paper, 2023). Esophageal squamous cell carcinoma (ESCC) is a type of esophageal carcinoma (EC) that can affect any part of the esophagus, but is usually located in the upper or middle third. "For instance, in the study of esophageal squamous cell carcinoma (ESCC), down-regulated TOB1 expression was found to be correlated with the unfavorable prognosis of tumor patients." (PMID 38062199, 2023).
germ cell cancer (1 paper, 2020). "Both tissue and sera from gastric and germ cell cancer patients exhibit elevated miR-371-3, which promotes tumor growth and metastasis by directly targeting tumor-suppressor gene TOB1 (transducer of ERBB2, 1)." (PMID 32660045, 2020).
leukemia (1 paper, 2015). A malignant (clonal) hematologic disorder, involving hematopoietic stem cells and characterized by the presence of primitive or atypical myeloid or lymphoid cells in the bone marrow and the blood. "In our study, we tested several dysregulated genes associated with leukemia by microarray data analysis, including MPL, GADD45g, TOB1, SLA, and ETS1, and mainly focused on MPL, which was reduced by PARP-1 inhibition." (PMID 26314963, 2015).
lymphopenia (1 paper, 2014). Reduction in the number of lymphocytes. "We showed previously that Tob1-deficient T cells expanded briskly under conditions of lymphopenia-induced proliferation (2 weeks after adoptive transfer into lymphodepleted SCID hosts)." (PMID 24945807, 2014).
metastatic disease (1 paper, 2016). "The integrated genetics and gene expression analysis that initially identified Cnot2 also implicated other genes associated with RNA deadenylation (Cnot8, Angel2, Tob1) as potential modulators of metastatic disease, suggesting that this function of CCR4-NOT might be a critical determinant." (PMID 26807845, 2016).
Obesity (1 paper, 2019). Accumulation of substantial excess body fat. "The Tob1 pathway may contribute to obesity through the MAPK pathway." (PMID 31118946, 2019). "As a repressor of the p38/MAPK pathway, TOB1 can suppress p38/MAPK signaling by decreasing phosphorylation of p38 and ATF2; p38/MAPK acts as an enhancer of adipogenesis contributes to obesity." (PMID 31118946, 2019).
osteoarthritis (1 paper, 2005). A noninflammatory degenerative joint disease occurring chiefly in older persons, characterized by degeneration of the articular cartilage, hypertrophy of bone at the margins and changes in the synovial membrane. "Our data, together with the knowledge from other cellular systems in the literature, suggest that Tob1 is a key molecule in the scenario of cellular alterations of osteoarthritis." (PMID 15743474, 2005). "In many respects the downregulation of Tob1 fits well into the scenarios taking place during osteoarthritis (validation level III), which suggests that Tob1 is a potential key molecule of cell phenotype regulation in osteoarthritic chondrocytes." (PMID 15743474, 2005).
osteopetrosis (1 paper, 2005). Osteopetrosis, also known as marble bone disease, is a descriptive term that refers to a group of rare, heritable disorders of the skeleton characterized by increased bone density on radiographs. "Tob1-knockout mice develop osteopetrosis due to a lack of inhibition of BMP-stimulated bone growth." (PMID 15743474, 2005).
osteoporosis (1 paper, 2023). A condition of reduced bone mass, with decreased cortical thickness and a decrease in the number and size of the trabeculae of cancellous bone (but normal chemical composition), resulting in increased fracture incidence. "The vital functionality of TOB1 has been evident in miR-26a-mediated osteogenesis in osteoporosis." (PMID 37268992, 2023).
osteosarcoma (1 paper, 2021). A usually aggressive malignant bone-forming mesenchymal neoplasm, predominantly affecting adolescents and young adults. "GSEA revealed enrichment of gene sets associated with the CTLA4 pathway, TOB1 pathway, cell aggregation, antimicrobial humoral immune response, and EMT in high-risk osteosarcoma patients." (PMID 34095215, 2021).
pancreatic adenocarcinoma (1 paper, 2020). "We also analyzed the data in The Cancer Genome Atlas‐Pancreatic adenocarcinoma (TCGA‐PAAD), and found that TOB1 was higher in cancer tissues (t = −2.208, P = .029)." (PMID 31891232, 2020).
prostate carcinoma (1 paper, 2020). A carcinoma that arises from epithelial cells of the prostate gland. "Signature tumor suppressor genes of prostate cancer such as Rb, PTEN, Caspase 1, and Tob-1 were underexpressed in LPB-Tag tumors but were overexpressed in the prostates of LPB-TagCTRKO genotype." (PMID 32180899, 2020).
rectal mucinous adenocarcinoma (1 paper, 2017). "It was shown that TOB1 was increased in rectal mucinous adenocarcinoma from Kaiser’s study." (PMID 28922388, 2017).
thyroid (1 paper, 2017). "Decreased TOB1 expression and increased TOB1 phosphorylation has been observed in lung and thyroid cancer." (PMID 29088861, 2017).
triple-negative breast carcinoma (1 paper, 2021). An invasive breast carcinoma which is negative for expression of estrogen receptor (ER), progesterone receptor (PR), and human epidermal growth factor receptor 2 (HER2). "LncRNA WEE2-AS1 was shown to be upregulated in triple-negative breast cancer and to act as an oncogene in the miR-32-5p/TOB1 axis." (PMID 37305396, 2021).
tumor (34 papers, 2011 to 2025). "We investigated the effect of TOB1 subcellular localization on the phenotype of tumor cells by mutating the NLS and NES sequences of TOB1 and stably overexpressing mutant TOB1 in AGS cells in vitro." (PMID 29088861, 2017). "Our results indicate that decreased TOB1 expression and increased nuclear p-TOB1 were associated with a malignant tumor phenotype and poor survival in GC patients." (PMID 29088861, 2017). "We investigated the expression of TOB1 and p-TOB1 in a cohort of 341 GC patients and found that the subcellular localization of TOB1 and p-TOB1 was associated with specific tumor types and patient survival." (PMID 29088861, 2017). "The following section will shed light on the molecular mechanisms associated with TOB1 tumor suppressor function." (PMID 26694352, 2015). "The purpose of this review is to delineate the molecular mechanisms underlying TOB1 tumor suppressor functions." (PMID 26694352, 2015). "We next determined if dual deficiencies of Nfatc2 and Tob1 would exacerbate the parenchymal lymphoid infiltration or accelerate tumor development." (PMID 24945807, 2014). "Tob1 is associated with the regulation of tumor cell proliferation and invasion, which may also contribute to the inhibition of cancer migration and metastasis." (PMID 40918450, 2025). "Remarkably, regardless of whether it pertained to the high neutrophils group (P < 0.001) or the low neutrophils group (P = 0.012), the subgroup of high TOB1 exhibited an increased tumor mutation burden (TMB)." (PMID 38617839, 2024). "Transducer of ERBB2 (TOB1) encodes a protein thought to function as a tumour suppressor." (PMID 33294012, 2020). "Thus, decreased TOB1 expression and increased phosphorylation of nuclear TOB1 is associated with aggressive tumor behavior and poor prognosis in intestinal type GC." (PMID 29088861, 2017). "Based on the recent understanding of TOB1, a putative role of TOB1 may be associated with tumor suppressor SMAD4 and oncogenic CTNNB-mediated signaling, likely including SMAD4-mediated suppression of AURKA-CTNNB activation." (PMID 26694352, 2015). "It has been shown that Tob1 knockdown can promote tumor cell migration and invasion in gastric and lung cancer cells." (PMID 40918450, 2025). "The expression analysis of key genes (PNRC1, HERPUD1, TP53INP2, Tob1, and SAT1), which is typically silenced in various tumour tissues and associated with poor prognosis and short survival time, revealed their upregulation upon 24 h treatment with L1." (PMID 39861074, 2024). "The main function of TOB1 is to inhibit tumor cell proliferation and promote tumor cell apoptosis through multiple signaling pathways." (PMID 38512977, 2024). "In other words, TOB1 extends the lifespan of neutrophils, leading to their accumulation, potentially facilitating the interaction between neutrophils and tumor cells." (PMID 38617839, 2024). "Subsequent experiments revealed that, following stimulation with the supernatant of tumor tissue culture, the levels of TOB1 protein and mRNA in neutrophils decreased, accompanied by enhanced apoptosis." (PMID 38617839, 2024). "Fluorescence imaging showed LC3 puncta at 48 h, and these puncta increased significantly at 72 h after TOB1 transfection compared with control tumor cells." (PMID 35186488, 2022). "BTG proteins are important regulators of cell cycle progression and TOB1 acts as a tumour suppressor in MCF-7 cells by inducing arrest at G1-S phase through upregulation of P27 and decreased activity of ERK2 and AKT." (PMID 29662623, 2018). "Endogenous p-TOB1 was primarily concentrated in the nuclei of AGS and HGC-27 cells, but was only present at low levels in GES-1 control cells, suggesting that the ratio of p-TOB1 to TOB1 contributes to the GC malignant tumor phenotype." (PMID 29088861, 2017). "In contrast, the expression of p-TOB1 in GC cell nuclei was associated with TNM stage, depth of invasion, and differentiation of the tumor." (PMID 29088861, 2017).